STAP1 (signal transducing adaptor family member 1)
Description:
In BCR signaling, appears to function as a docking protein acting downstream of TEC and participates in a positive feedback loop by increasing the activity of TEC.
Synonyms: STAP-1; BRDG1
Tractability: Small molecule: it has a high-quality binding pocket. PROTAC: its protein half-life has been measured.
Gene: Protein-coding gene on chromosome 4 (67,558,482 to 67,607,343, forward strand). Ensembl gene ENSG00000035720.
Subcellular location: Nucleus; Cytoplasm; Mitochondrion
Subcellular location (Human Protein Atlas): Cytosol; Nuclear bodies
Gene Ontology:
Molecular function: phosphotyrosine residue binding; protein binding; protein kinase binding; protein tyrosine kinase activator activity; signaling adaptor activity; phospholipid binding; transmembrane receptor protein tyrosine kinase adaptor activity; macrophage colony-stimulating factor receptor binding; protein-macromolecule adaptor activity; receptor tyrosine kinase binding
Biological process: positive regulation of B cell receptor signaling pathway; cell surface receptor protein tyrosine kinase signaling pathway; cellular response to lipopolysaccharide; negative regulation of macrophage chemotaxis; negative regulation of macrophage colony-stimulating factor signaling pathway; negative regulation of ruffle assembly; positive regulation of gene expression; positive regulation of microglial cell activation; positive regulation of microglial cell mediated cytotoxicity; positive regulation of phagocytosis, engulfment; negative regulation of microglial cell migration
Cellular component: cytoplasm; cytosol; mitochondrion; nuclear body; nucleus; protein-containing complex
Genetic constraint (gnomAD): Loss-of-function variants: 14 observed, 22.29 expected, observed/expected ratio (o/e) 0.63, 90% interval 0.41 to 0.98. The upper end of that interval is the gene's LOEUF score, 0.98, which puts it in group 4 of 6, group 1 being the genes least tolerant of losing a copy. Missense variants: 266 observed, 266.71 expected, observed/expected ratio (o/e) 1, 90% interval 0.9 to 1.1. Synonymous variants: 96 observed, 93.84 expected, observed/expected ratio (o/e) 1.02, 90% interval 0.87 to 1.21.
Homologues: Orthologues: chimpanzee STAP1 (99% identical), macaque STAP1 (97% identical), mouse Stap1 (84% identical), pig STAP1 (84% identical), dog STAP1 (83% identical), rabbit STAP1 (81% identical), rat Stap1 (81% identical), guinea pig STAP1 (77% identical), tropical clawed frog stap1 (40% identical). Paralogues in human: STAP2 (31% identical).
Diseases named in the same sentence as STAP1 in open-access papers:
STAP1 is named in the same sentence as 45 diseases in open-access papers, as found by Europe PMC text mining. Sharing a sentence is not in itself a finding about the gene and the disease. The quoted sentences say what the papers report.
Hypercholesterolemia (9 papers, 2019 to 2023). An increased concentration of cholesterol in the blood. "Two recent studies independently identified that mutations in Signal Transducing Adaptor family member 1 [STAP1; also known as BRDG1 (BCR downstream signaling protein 1) or stem cell adaptor protein 1] are also associated with familial hypercholesterolemia." (PMID 36293233, 2022). "In a sample of German patients with hypercholesterolemia, a new mutation in STAP1—c.139A>G (p.(T47A), rs793888522)—was found to be co-segregated in the family of a patient with myocardial infarction." (PMID 31795497, 2019). "As STAP1 is mainly expressed in B cells, it is of great interest to investigate the mutation of STAP1, which will enhance our understanding of the capacity of antibody and cytokine production by B cells in regulating hypercholesterolemia." (PMID 36293233, 2022). "It is reported that STAP1 was associated with hypercholesterolemia." (PMID 36713363, 2022). "This study tested the hypothesis that loss of Stap1 can lead to hypercholesterolemia using Stap1−/− mice." (PMID 33228548, 2020). "The link between STAP1 and hypercholesterolemia was proposed when some FH4 patients were reported to have variants of the gene, in the absence of changes in known hyperlipidemia loci." (PMID 33228548, 2020). "Other identified genes that were less frequently detected in familial hypercholesterolemia encode apolipoprotein E (APOE) and the signal-transducing adaptor family member 1 (STAP1)." (PMID 32528276, 2020). "It was initially hypothesized that extra-hepatic mechanisms were responsible for STAP1 mediated hypercholesterolemia due to the fact that liver distribution was low." (PMID 33228548, 2020). "Genetic changes in STAP1 are therefore unlikely to be cause of familial hypercholesterolemia and variants reported in such rare families may represent a spurious association." (PMID 33228548, 2020).
autoimmune hepatitis (3 papers, 2020 to 2021). Hepatitis caused by autoantibodies. "In the present study we demonstrated that STAP-1 is required for the maintenance/activation of iNKT cells, and has a capacity to modify autoimmune hepatitis." (PMID 33175848, 2020). "Additional detailed research will clarify the molecular mechanisms involved in STAP-1-mediated regulation of signal transduction in iNKT cells, and will provide insights into the development of a novel therapeutic strategy for autoimmune hepatitis." (PMID 33175848, 2020). "We also found the role of STAP-1 in NKT cell-mediated autoimmune hepatitis (manuscript in preparation)." (PMID 32661325, 2020). "Present data suggest new functions of STAP-1 in vivo and in vitro; in addition, STAP-1 is likely to be a key player in the pathogenesis of autoimmune hepatitis." (PMID 33175848, 2020). "Thus, manipulation of STAP-1 may control iNKT cell activation and autoimmune hepatitis development in vivo." (PMID 33175848, 2020).
glioma (3 papers, 2023 to 2026). A benign or malignant brain and spinal cord tumor that arises from glial cells (astrocytes, oligodendrocytes, ependymal cells). "In conclusion, we found that STAP1 expression in glioma-associated microglia is positively correlated with the degree of malignancy and poor prognosis of glioma." (PMID 37462801, 2023). "STAP1 expression in glioma-associated microglia is positively correlated with the degree of malignancy and poor prognosis of glioma." (PMID 37462801, 2023). "The Cancer Genome Atlas and Chinese Glioma Genome Atlas databases were used to investigate the association between STAP1 mRNA levels and clinical parameters (grades, mutations in isocitrate dehydrogenase, and overall survival)." (PMID 37462801, 2023). "We have demonstrated that STAP1 promotes microglial M2-like polarisation and is associated with the degree of glioma malignancy." (PMID 37462801, 2023). "STAP1 is positively associated with the degree of glioma malignancy and may represent a potential novel therapeutic target for glioma." (PMID 37462801, 2023). "Moreover, isocitrate dehydrogenase (IDH) wild type glioma, a subtype associated with poor outcomes, showed higher expression levels of STAP1 than IDH mutant glioma." (PMID 37462801, 2023). "These fundings indicate that STAP1 may be associated with the degree and poor prognosis of malignancy of glioma." (PMID 37462801, 2023). "To validate this result, we assessed the transcript levels of STAP1 in glioma samples from the TCGA and CGGA datasets." (PMID 37462801, 2023). "Based on isolated GAMs, we performed transcriptome sequencing of GAMs and found that STAP1 mRNA levels were higher in GAMs of grade 4 glioma than in grade 2–3 glioma." (PMID 37462801, 2023). "The aim of the present study was to investigate the relationship between STAP1 expression levels and the degree of glioma malignancy." (PMID 37462801, 2023). "Immunofluorescence staining showed a higher expression level of STAP1 in the microglia of grade 4 gliomas than those of grade 2–3 gliomas." (PMID 37462801, 2023). "Based on the Brain Cancer Immunology Atlas (BCIA) at Huashan Hospital, Fudan University, we found that STAP1 is differentially expressed in different grades of glioma." (PMID 37462801, 2023). "We then collected 26 glioma tissue samples for immunohistochemistry and the protein level of STAP1 was significantly higher in patients with grade 4 glioma than those with grade 2–3 glioma." (PMID 37462801, 2023). "Compared to grade 2–3 gliomas, the mRNA levels of STAP1 were higher in grade 4 gliomas." (PMID 37462801, 2023). "Furthermore, the Kaplan-Meier survival curves indicated that the OS of the control group was longer than that of the high-STAP1 group in orthotopic glioma models." (PMID 37462801, 2023). "Therefore, targeting STAP1 to enhance phagocytosis and reverse the M2-like polarisation of microglia is a promising anti-tumour strategy for glioma treatment." (PMID 37462801, 2023). "This study suggests STAP1 as a potential therapeutic target for glioma in the future." (PMID 37462801, 2023). "Therefore, we mixed GL261 and BV-2-STAP1 cells and injected them into the murine right striatum to establish an orthotopic glioma model, in which the TME highly expresses STAP1." (PMID 37462801, 2023). "Similarly, low expression level of STAP1 prolonged the OS of patients with grade 2–3 glioma." (PMID 37462801, 2023). "Similarly, our findings also indicated that STAP1 may promote glioma progression." (PMID 37462801, 2023). "However, compared to STAP2, there have been few studies on STAP1, and to date, no studies on STAP1 in GAMs and glioma have been reported." (PMID 37462801, 2023).
Hepatitis (2 papers, 2020 to 2022). Inflammation of the liver. "We aimed to investigate the functions of STAP-1 in invariant natural killer T (iNKT) cells and iNKT cell-dependent hepatitis." (PMID 33175848, 2020). "In summary, STAP-1 regulates Con A-induced and/or α-GalCer-induced hepatitis in which iNKT cells have important roles." (PMID 33175848, 2020). "To confirm the effects of STAP-1 on iNKT cell-mediated hepatitis, we measured necrotic areas of livers in α-GalCer-treated WT, S1KO, and S1Tg mice." (PMID 33175848, 2020). "α-GalCer is a stimulator, which is more restricted to iNKT than Con A. To investigate whether STAP-1 is a critical adaptor protein to induce iNKT cell-mediated hepatitis, the effects of STAP-1 on α-GalCer-induced hepatitis were assessed." (PMID 33175848, 2020). "Two events that may be related to Con A-induced and/or α-GalCer-induced hepatitis were influenced by STAP-1 manipulation." (PMID 33175848, 2020). "Therefore, in this study, we collected new patient samples to investigate the correlation between the methylation of another gene, STAP1, as well as AHNAK, and the progression of hepatitis and HCC and to assess the diagnostic effect of the combination using the genes STAP1 and AHNAK." (PMID 36713363, 2022).
hepatitis B (2 papers, 2018 to 2022). "We performed a multifactorial ANOVA analysis on the methylation values of STAP1 as a dependent variable and diagnosis (HCC versus non-HCC including hepatitis B), sex, and age as independent variables as well as interactions between sex, age, and diagnosis." (PMID 29375724, 2018).
hepatocellular carcinoma (2 papers, 2022 to 2025). A malignant tumor that arises from hepatocytes. "The methylation of STAP1 in peripheral blood immune cells shows potential diagnostic and prognostic values for treating hepatocellular carcinoma within five cm." (PMID 40936767, 2025). "In hepatocellular carcinoma, the aberrant methylation of STAP1 may also contribute to hepatocarcinogenesis via these signaling pathways." (PMID 36713363, 2022).
hepatopathy (2 papers, 2022 to 2024). "The combination of methylation of STAP1 and AHNAK indeed achieved a better performance in distinguishing the different types of hepatopathy patients, which suggests the diagnostic value of STAP1." (PMID 36713363, 2022). "The GEO datasets also supported that the methylation of AHNAK and STAP1 was associated with different types of hepatopathy." (PMID 36713363, 2022). "Additionally, the combination of AHNAK and STAP1 methylation in PBLs has shown potential as a diagnostic marker for HBV-related hepatopathy, and LGF2 methylation levels were found to be altered in peripheral blood cells." (PMID 38397459, 2024). "We concluded that combination of AHNAK and STAP1 methylation in peripheral blood immune cells can be used as a diagnostic marker for HBV related hepatopathy and STAP1 methylation may be a potential prognostic marker for HBV related HCC." (PMID 36713363, 2022). "The combination of AHNAK and STAP1 methylation was able to predict differrent HBV related hepatopathy." (PMID 36713363, 2022). "Therefore, our study is the first to discover the relationship of methylation of STAP1 with hepatopathy and HCC." (PMID 36713363, 2022). "Although we had identified that the methylation of AHNAK was a good diagnostic marker for hepatopathy, here we speculate that there was also another marker, STAP1, whose methylation also involved in the detection of hepatopathy." (PMID 36713363, 2022). "Especially for STAP1, little is known about its function, and thus in the future, an experimental investigation about it should be carried out to understand its functional role in HBV-related hepatopathy." (PMID 36713363, 2022). "However, there were a few reports about STAP1 in cancer and no publication for hepatopathy." (PMID 36713363, 2022).
leukemia (2 papers, 2020 to 2026). A malignant (clonal) hematologic disorder, involving hematopoietic stem cells and characterized by the presence of primitive or atypical myeloid or lymphoid cells in the bone marrow and the blood. "In the secondary BM transplantation (BMT), no mice injected with STAP-1 KO GFP+ cells developed CML, while 36.7% of the mice transplanted with GFP+ cells derived from WT mice developed leukemia within 28 days." (PMID 32661325, 2020).
liver cancer (2 papers, 2018 to 2022). An epithelial or non-epithelial malignant neoplasm that arises from the liver. "Methylation level of STAP1 in PBMC was positively correlated with the course of liver cancer." (PMID 36713363, 2022). "In summary, STAP1 provides proof of principle for potential DNA methylation biomarkers in HCC peripheral white blood cells and for discriminating Stage 1 from chronic hepatitis and healthy controls which is a critical hurdle in early diagnosis of liver cancer." (PMID 29375724, 2018).
abscess (1 paper, 2023). An inflammatory process characterized by the accumulation of pus within a newly formed tissue cavity which is the result of a bacterial, fungal, or parasitic infection or the presence of a foreign body. "On day 6, abscess areas of < 10 mm2 remained with the StAP1 treatment, which was close to that of the initial day in the PBS group." (PMID 37840707, 2023). "Compared to the control group, we observed that administration of phage StAP1 significantly facilitated the resolution of abscesses." (PMID 37840707, 2023). "Furthermore, histology analysis revealed that there was obvious abscess formation and inflammatory cell infiltration in the PBS group, while the degree of tissue damage was significantly reduced on account of StAP1 treatment." (PMID 37840707, 2023).
Allergy (1 paper, 2020). An allergy is an immune response or reaction to substances that are usually not harmful. "Although several reports have suggested some functions of STAP-1, it is unknown whether STAP-1 is involved in the pathogenesis of immune diseases such as autoimmunity and allergy." (PMID 33175848, 2020).
atherosclerosis (1 paper, 2020). A disease characterized by the build-up of fatty material and calcium deposition in the arterial wall resulting in partial or complete occlusion of the arterial lumen. "Some studies have associated STAP1 variations with cardiovascular disease, and immune cells have been linked with atherosclerosis and FH." (PMID 33228548, 2020).
autoimmune disease (1 paper, 2022). A disorder resulting from loss of function or tissue destruction of an organ or multiple organs, arising from humoral or cellular immune responses of the individual to their own tissue constituents. "STAP1 and DUSP1 are significantly associated with anti-inflammatory responses and immune infiltration in human autoimmune diseases." (PMID 35581549, 2022).
chronic myeloid leukemia (1 paper, 2022). "We previously reported that STAP-1 is a key molecule that regulates chronic myeloid leukemia (CML) stem cell survival by increasing the anti-apoptotic gene expression via enhanced STAT5 activity." (PMID 36551835, 2022).
colorectal cancer (1 paper, 2016). A primary or metastatic malignant neoplasm that affects the colon or rectum. "Here, we report that human colorectal cancer (CRCs) cell lines demonstrate differential dependency on URI1 and on the URI1 partner PFD STAP1 for survival, suggesting that this differential vulnerability of CRC cells is directly linked to URI1C chaperone function." (PMID 27105489, 2016).
coronary artery diseases (1 paper, 2023).
degenerative disc disease (1 paper, 2020). "By RT-qPCR, the expression of STAP1 was found to be significantly decreased due to degenerative disc disease (P<0.001), thereby suggesting that STAP1 could be inhibited by silencing CircGLCE or by overexpressing miR-587." (PMID 33159017, 2020).
hyperlipidemia (1 paper, 2020). "Therefore, we sought out to understand the STAP1 role by using a mouse knockout model, to ask if loss of STAP1 would lead to hyperlipidemia." (PMID 33228548, 2020). "Thus, even for missense variants of STAP1 to have a pathological role in causing hyperlipidemia in humans, a mechanistic pathway to do so would need to be identified." (PMID 33228548, 2020).
intervertebral disc degeneration (1 paper, 2020). "To summarize, CircGLCE alleviates intervertebral disc degeneration by regulating apoptosis and matrix degradation through the targeting of miR-587/STAP1." (PMID 33159017, 2020).
liver cirrhosis (1 paper, 2022). "The current study aimed to explore the diagnostic and prognostic value of STAP1 methylation in liver cirrhosis and HCC combined with AHNAK." (PMID 36713363, 2022). "In the GSE60753 data, there was a significant difference in STAP1 methylation level among liver cirrhosis and HCC (Kruskal−Wallis test, p = 1.2e−06)." (PMID 36713363, 2022). "In order to confirm the association of STAP1 and AHNAK with liver diseases, we further analyzed the AHNAK and STAP1 methylation levels in the different types of liver cirrhosis or HCC using the GEO datasets." (PMID 36713363, 2022). "However, in the public data, there was hyper-methylation of both AHNAK and STAP1 in liver cirrhosis and hypo-methylation both in the HCC and adjacent tissues." (PMID 36713363, 2022).
liver disease (1 paper, 2022). "In addition, our previous research also showed that STAP1 methylation in PBMC is also associated with the progression of hepatitis B virus (HBV)-related liver diseases." (PMID 36713363, 2022). "The STAP1 methylation level was positively correlated with the severity of the liver disease not only in the PBMC but also the T cells, while AHNAK showed a negative correlation." (PMID 36713363, 2022). "We also evaluated the differences and changes of methylation and expression of AHNAK and STAP1 at different stages of liver disease using the TCGA and GEO public datasets." (PMID 36713363, 2022).
lung adenocarcinoma (1 paper, 2022). A carcinoma that arises from the lung and is characterized by the presence of malignant glandular epithelial cells. "Although STAP1 is reported to be involved in B cell receptor signaling and in the prognosis gene signature of lung adenocarcinoma, the role of STAP1 in HCC is not clear." (PMID 36713363, 2022).